CTLA4 (cytotoxic T-lymphocyte associated protein 4)
Diseases named in the same sentence as CTLA4 in open-access papers (continued):
Sharing a sentence is not in itself a finding about the gene and the disease.
hepatocellular carcinoma (155 papers, 2012 to 2026). A malignant tumor that arises from hepatocytes. "In Chinese Han population and Egyptian, rs231775 of CTLA4 gene has found involvement in hepatocellular carcinoma and a direct association with cancer." (PMID 39854591, 2025). "Regulatory T cells frequently exhibit high expression of PD-L1 and cytotoxic T-lymphocyte-associated protein 4 (CTLA-4), thereby promoting the immune escape of hepatocellular carcinoma cells." (PMID 40539064, 2025). "In this study, we established a monoclonal hepatocellular carcinoma cell line (Hepa1-6 #12) and analyzed the mechanisms associated with anti-CTLA-4 Ab treatment." (PMID 39106430, 2024). "This study aimed to investigate the prognostic potential of programmed cell death protein 1 (PD-1) and cytotoxic T-lymphocyte-associated protein 4 (CTLA-4) gene expressions in peripheral blood mononuclear cells for hepatocellular carcinoma." (PMID 38672574, 2024). "For example, combination of cytotoxic T-lymphocyte-associated protein 4 (CTLA-4) inhibitor, tremelimumab, and PD-1 inhibitor, durvalumab, was approved for treating patients with unresectable hepatocellular carcinoma in 2022." (PMID 37831146, 2023). "There is only a limited number of studies investigating CTLA-4 gene polymorphisms and risk of hepatocellular cancer (HCC) available in the literature." (PMID 33519815, 2020). "Moreover, MIAT in hepatocellular carcinoma is linked to increased expression of immune checkpoint molecules (PD-1, PD-L1, CTLA4) and found in populations of immune cells associated with immune suppression." (PMID 41154428, 2025). "At least for ELOVL1, a higher expression in hepatocellular carcinoma results in cancer immune evasion, including an increased expression of programmed death-ligand 1 (PD-L1) and cytotoxic T-lymphocyte-associated protein 4 (CTLA4)." (PMID 36291290, 2022). "Similarly, high expression of OX40, CD276, CTLA4 was significantly associated with poor prognosis of hepatocellular carcinoma." (PMID 34869039, 2021). "Relationship of genetic polymorphisms and soluble CTLA-4 (sCTLA-4) with clinicopathological features in hepatocellular carcinoma (HCC) patients." (PMID 41303553, 2025). "Over the past decade, immune checkpoint inhibitors (ICIs) targeting PD-1, PD-L1, and CTLA-4 have become key treatments for many solid cancers, including hepatocellular carcinoma (HCC)." (PMID 41186530, 2026). "Dual checkpoint inhibition with durvalumab (PD-L1 inhibitor) and tremelimumab (CTLA-4 inhibitor) has been evaluated in unresectable hepatocellular carcinoma (HCC) through a phase 1/2 study followed by a confirmatory phase 3 trial." (PMID 41159031, 2025). "Tremelimumab, another ICIs targeting CTLA-4, was approved in combination with durvalumab (anti-PD-L1) for treating unresectable hepatocellular carcinoma (HCC) in the USA and Japan as the first-line treatment of adults." (PMID 40636119, 2025). "Then, a combination of tremelimumab and durvalumab received approval in the United States for treating unresectable hepatocellular carcinoma in 2022, signifying the clinical transition of combining anti-CTLA-4 and anti-PD-1 antibodies." (PMID 38592036, 2024). "Our results revealed that IFN-g produced by T-helper 1 (Th1) plays an important role in the elimination of hepatocellular carcinoma mediated by an anti-CTLA-4 Ab." (PMID 39106430, 2024). "Two FDA-approved anti-CTLA-4 antibodies, Ipilimumab and tremelimumab, have shown safety and efficacy in treating HBV/HCV infections and associated hepatocellular carcinoma." (PMID 38592036, 2024). "Since 2017, immune checkpoint inhibitors, such as nivolumab, pembrolizumab, camrelizumab and atezolizumab, which are PD-1/PDL-1 and CTLA-4 inhibitors, have been widely applied to treat hepatocellular carcinoma." (PMID 39052085, 2024). "The use of drugs targeting immune checkpoints like PD-L1, PD-1, and CTLA-4, has been a significant development in the treatment of liver cancer, particularly hepatocellular carcinoma (HCC)." (PMID 39295859, 2024).
hepatocellular carcinoma (continued). "Inhibitors of PD-1, PDL-1, and CTLA-4 are the backbone of clinical practice or of systemic therapies in development for hepatocellular carcinoma." (PMID 37234162, 2023). "A phase I clinical trial has also confirmed that the combined strategy of RFA and anti-CTLA-4 treatments against human hepatocellular carcinoma can present a synergistic anti-tumor effect and an increasing number of CD8+TILs." (PMID 36900218, 2023). "A previous meta-analysis reported that the CTLA-4 CT60 is associated with an increased risk of skin cancer, while another study showed an increased risk of hepatocellular carcinoma (HCC)." (PMID 37107632, 2023). "This phase Ib/II study was the first study to examine the novel cadonilimab plus lenvatinib combination regimen, which involved dual PD-1/CTLA-4 inhibitors and an antiangiogenic agent in treating advanced hepatocellular carcinoma (aHCC)." (PMID 37942328, 2023). "RFA has an immune effect in liver tumors, and its combination with a CTLA-4 inhibitor had a clinical benefit in a phase 1 trial of hepatocellular carcinoma." (PMID 35407555, 2022). "The triple therapy with Belinostat, anti-CTLA-4 and anti-PD-L1 resulted in complete tumour rejection in the hepatocellular carcinoma model." (PMID 35459932, 2022). "Since the first trial with tremelimumab, a cytotoxic T-lymphocyte-associated protein 4 inhibitor, increasing evidence has confirmed that these drugs can significantly extend the survival of patients with advanced hepatocellular carcinoma (HCC)." (PMID 34361985, 2021). "Another group of mice bearing subcutaneous Hepa1-6 hepatocellular carcinoma tumors were given three doses of CTLA-4 monoclonal antibody prior and one post histotripsy treatment." (PMID 34136405, 2021). "More recently, a study using a mouse model of hepatocellular carcinoma showed that systemic HDACi (Belinostat) combined with the simultaneous blockade of CTLA-4 led to the decrease of regulatory T cells and complete tumor rejection." (PMID 32500025, 2020). "It has been proposed that cytotoxic T-lymphocyte antigen 4 (CTLA-4) may attenuate the T-cell activation threshold, thereby decreasing the antitumor response and conferring susceptibility to hepatocellular carcinoma (HCC)." (PMID 31335675, 2019). "We investigated the suppressive effect of siRNA-mediated co-inhibition of PD-1 and CTLA-4 expression on H22 hepatomas in mice." (PMID 30564277, 2018). "In a study of twenty one patients with hepatocellular carcinoma and chronic hepatitis C who received tremelimumab, another CTLA-4 blocking antibody, 45% experienced a transient grade three or higher rise in liver transaminases after the first dose." (PMID 25317333, 2014). "Six patients had SD with INCAGN02385 treatment; 5 of these patients had received previous treatment with a PD-1-targeted ICI (nivolumab or pembrolizumab), including one patient with hepatocellular carcinoma who had SD with combined PD-1 plus CTLA-4-targeted treatment (nivolumab plus ipilimumab)." (PMID 40631774, 2025). "In hepatocellular carcinoma, MDK was associated with enhanced Treg and myeloid-derived suppressor cell (MDSC) infiltration and enhanced expression of immune checkpoint molecules such as cytotoxic T-lymphocyte-associated protein 4 (CTLA4)." (PMID 40429950, 2025). "The immune system of affected individuals has an important role in the malignant transformation, and is nowadays the target of various checkpoint inhibitors (for example PD-L1 or CTLA-4) as part of adjuvant or neoadjuvant therapeutic strategies for hepatocellular carcinoma (HCC)." (PMID 40107998, 2025). "Additionally, risk scores were significantly associated with immune checkpoint molecules PD-1, PD-L1, and CTLA4, which potentially links paraspeckle gene expression to immune evasion in hepatocellular carcinoma." (PMID 39133261, 2024).
hepatocellular carcinoma (continued). "In tumors such as pancreatic adenocarcinoma, hepatocellular carcinoma, and pancreatic cancer, the scores of m6A-modified regulatory genes are significantly correlated with the expression of CTLA-4 and can be used to predict prognosis and response to immunotherapy." (PMID 39372415, 2024). "Previous work has shown that there is a specific increase in expression of CTLA4, a negative regulator of T-cell receptor signaling, during tumor progression in a KRAS-driven murine PDAC model and that induction of MYC in a model of hepatocellular carcinoma elevates CTLA4 expression on T-cells." (PMID 38365788, 2024). "Moreover, the pan-HDAC inhibitor Belinostat improves the efficacy of anti-CTLA-4 therapy in the hepatocellular carcinoma model." (PMID 35459932, 2022). "Indeed, combining RFA with a CTLA-4 inhibitor has demonstrated clinical activity in a phase 1 trial of hepatocellular carcinoma with a clear increase in CD8+ T-cells in patients who showed a clinical benefit." (PMID 34502076, 2021). "Moreover, the results obtained previously with anti-CTLA-4 antibody use in patients with advanced hepatocellular carcinoma encouraged the use of a combination of anti-CTLA-4 and anti-PD-1 antibodies with the pan-HDACi, belinostat." (PMID 33024443, 2020). "Dasatinib, an indirect STAT3 inhibitor, significantly facilitated anti-CTLA-4 immunotherapy in head and neck squamous cell carcinoma, while the combined blockade of IL-6 and PD-L1 remarkably inhibited the growth of pancreatic ductal adenocarcinoma and hepatocellular carcinoma." (PMID 40963562, 2025). "In this study, we explored the feasibility of using oncolytic peptide LTX-315 plus an anti-cytotoxic T lymphocyte antigen-4 (CTLA-4) antibody for inhibiting residual tumors after RFA of hepatocellular carcinoma (HCC)." (PMID 40222972, 2025). "Another study reported lower baseline fecal calprotectin levels in patients with hepatocellular carcinoma (HCC) who clinically benefited from the ICI therapy (anti-CTLA-4 and/or anti-PD-L1 therapy) in comparison to those with PD." (PMID 40869383, 2025). "Two CTLA-4-targeting antibodies, ipilimumab and tremelimumab, have received regulatory approval for the treatment of hepatocellular carcinoma (HCC) in combination regimens." (PMID 39833954, 2025). "Systemic therapy for advanced hepatocellular carcinoma (HCC) has progressed significantly, yet the management of immune-related adverse events (irAEs) remains a challenge, particularly with anti-CTLA-4 and anti-PD-L1 antibodies." (PMID 40632185, 2025). "It has been reported that targeting PD-1, PD-L1 or CTLA-4 may provide different outcomes in gastric cancer and hepatocellular carcinoma; thus, hypothesizing whether the application of different ICIs was associated with different efficacies in patients with GI cancer." (PMID 38183112, 2024). "Metformin changes the expression pattern of immune mediators in hepatocellular carcinoma (HCC) immune microenvironment, including PD-1, cytotoxic T lymphocyte antigen-4 (CTLA-4)." (PMID 36614197, 2023). "In the context of hepatocellular carcinoma (HCC), ELOVL1 appears to influence immune cell infiltration and the expression of immune checkpoint markers, such as programmed cell death-1 (PD-1) and cytotoxic T lymphocyte-associated protein-4 (CTLA-4)." (PMID 37981715, 2023). "The correlation between WNT signaling activation and resistance to immune checkpoint blockade, such as CTLA-4 and PD(L)-1, was identified in melanoma and hepatocellular carcinoma (HCC)." (PMID 36358276, 2022). "Another study explored hepatocellular carcinoma (HCC) in 42 patients who received either nivolumab monotherapy or anti-PD-1 (pembrolizumab) in combination with anti-CTLA-4 (ipilimumab)." (PMID 35641998, 2022).
hepatocellular carcinoma (continued). "CTLA-4 is another immunosuppressive molecule, and an in vitro experiment suggested that CD4+ CD25+ Tregs isolated from peripheral-blood mononuclear cells could upregulate the expression of CTLA-4 after being co-cultured with stably HBV-transfected human hepatoma cell lines." (PMID 32547550, 2020). "Furthermore, PD-1 blockade in vivo was well-tolerated and promoted virus control in a subset of HCV-infected patients whereas CTLA-4 blockade in patients with hepatocellular carcinoma and chronic hepatitis C was tolerated with antiviral and immune stimulatory effects." (PMID 25071758, 2014). "These strategies are supported by studies in hepatocellular carcinoma (HCC), where dual immunotherapy (anti-PD-L1/CTLA-4) with molecular agents improved antitumor response in patients with otherwise limited options." (PMID 41459545, 2025). "Additionally, analysis of the hepatocellular carcinoma (HCC) cohort from The Cancer Genome Atlas (TCGA) database showed that high mRNA expression-based stemness index (mRNAsi) risk score, an important index of CSCs, was associated with higher expression of CTLA-4." (PMID 41233805, 2025). "Recent advances in immune checkpoint inhibitors (ICIs), including programmed cell death protein 1 (PD-1)/programmed death ligand 1 (PD-L1) and cytotoxic T lymphocyte-associated antigen 4 (CTLA-4), have shown promise for improving the prognosis of patients with hepatocellular carcinoma (HCC)." (PMID 40796887, 2025). "For instance, in hepatocellular carcinoma (HCC), tumor-educated MAIT cells upregulate inhibitory molecules like PD-1, CTLA-4, and TIM-3, strongly decreasing IFNγ, IL17, GZM B, and perforin production." (PMID 40422223, 2025). "In the TME of colorectal cancer, hepatocellular carcinoma, and other malignancies, MAIT cells exhibit high expression levels of inhibitory receptors, such as PD‐1 and CTLA‐4, and tend to secrete IL‐17, which promotes angiogenesis and metastasis." (PMID 41179703, 2025). "Current immune-checkpoint blockade agents for hepatocellular carcinoma (HCC) treatment mainly consist of anti-PD-1/PD-L1 and anti-CTLA-4 antibodies." (PMID 39113701, 2024). "The purpose of this study was to develop a cell–cell interaction model that could predict a tumor’s response to radiotherapy (RT) combined with CTLA-4 immune checkpoint inhibition (ICI) in patients with hepatocellular carcinoma (HCC)." (PMID 37174706, 2023). "The most significant immune biomarkers for hepatocellular carcinoma were employed in immunotherapy, according to earlier research: PDCD1, CTLA4, HAVCR2/TIM3, and LAG3." (PMID 38248311, 2023). "In patients with hepatocellular carcinoma (HCC), neoplasm-localized MAIT cells exhibited upregulation of inhibitory immune molecules (e.g., PD-1, CTLA-4, and TIM-3) and secreted lower quantities of effector molecules (e.g., IFN-γ, granzyme B, and perforin)." (PMID 36463401, 2023). "In the case of hepatocellular carcinoma (HCC) patients, anti-PD-1, anti-PD-L1, and anti-CTLA-4 monoclonal antibodies are commonly used ICIs in clinical practice." (PMID 38169837, 2023). "Preclinical studies showed that IDO may lead to resistance to anti-CTLA-4 immune checkpoint therapy in hepatocellular carcinoma (HCC)." (PMID 34572263, 2021). "Preclinical and clinical studies also show that the immune checkpoint therapy provides a survival benefit for some significant number of patients with liver cancer, and a combination of anti-PD-1/PD-L1 and anti-CTLA-4 antibodies is an effective treatment strategy forhepatocellular carcinoma (HCC)." (PMID 30564277, 2018). "In hepatocellular carcinoma (HCC) and pancreatic cancer patients, two distinct FoxP3+/− TI Treg subsets exhibiting differential expression patterns of CTLA-4, PD-1, CD25 and CD69 were identified in tumor-infiltrating lymphocyte (TIL) populations." (PMID 27509527, 2016).
hepatocellular carcinoma (continued). "In hepatocellular carcinoma (HCC), tumor tissue localized MAIT cells also exhibited exhausted phenotype with upregulation of inhibitory immune molecules (PD-1, CTLA-4, and TIM-3) and secreted lower quantities of effector molecules (e.g., IFN-g, granzyme B, and perforin)." (PMID 38545100, 2024). "We found that T cell checkpoints CTLA-4, PD-1, and PD-L1 were closely related to ZNF765, and the number of multiple subtypes of T cells may have an effect on the prognosis of patients with hepatocellular carcinoma." (PMID 37400985, 2023). "Recently, another CTLA-4 antagonist, tremelimumab, received priority review in the US FDA, supporting the combination of anti-CTLA4 antibody, tremelimumab, and the anti-PDL-1 antibody durvalumab for the treatment of patients with unresectable hepatocellular carcinoma." (PMID 37427115, 2023). "In addition, TUBA1B has been shown to mediate the infiltration of several immune cells in hepatocellular carcinoma, including CD274 and CTLA4." (PMID 36140469, 2022). "Comparing both CTLA-4 antibodies revealed a clone dependent unspecific staining pattern in adrenal cortical adenoma (63%) for MSVA-152R and in pheochromocytoma (67%) as well as hepatocellular carcinoma (36%) for CAL49." (PMID 35091676, 2022). "Interestingly, in this respect, high Siglec-10 levels in hepatocellular cancer patients correlated with significantly higher expression of inhibitory receptor genes such as PD1, TIM3, CTLA-4, or LAG-3 in a more recent study." (PMID 35625912, 2022). "Dasatinib, an indirect STAT3 inhibitor against SRC/ABL, significantly facilitated anti-CTLA-4 immunotherapy in head and neck squamous cell carcinoma, while the combined blockade of IL-6 and PD-L1 remarkably inhibited the growth of pancreatic ductal adenocarcinoma and hepatocellular carcinoma (HCC)." (PMID 32972405, 2020). "More recently, another anti-CTLA-4 monoclonal antibody, tremelimumab, was approved as part of the STRIDE regimen, in which a single priming dose of tremelimumab is used in combination with repeated doses of durvalumab (anti-PD-L1 antibody) to treat unresectable hepatocellular carcinoma." (PMID 40561796, 2025). "Ipilimumab was approved by the FDA in 2011, yet the second anti-CTLA-4 monoclonal antibody, tremelimumab, was not approved until 2022 for the treatment of unresectable hepatocellular carcinoma, and then only in combination with the anti-PD-L1 antibody duralimumab." (PMID 38312352, 2024). "Moreover, the study showed that when healthy donor PBMCs were co-cultured with human hepatoma cells HepG2.2.15 (transfected with HBV) and its parental cell line HepG2, the Treg population increased and upregulated the expression of CTLA-4 on HepG2.2.15 compared with the HepG2 cells." (PMID 37243227, 2023). "SATB1 overexpression not only reduced expression of multiple inhibitory receptors (PD-1, CTLA-4, TIM3, and LAG-3) but also promoted a central memory phenotype, enhancing cytokine production and cytotoxicity against hepatocellular carcinoma (HCC) cells in vitro." (PMID 41372119, 2025). "STAT1 was significantly positively correlated with PD1 (r = 0.448), PD-L1 (r = 0.444), CTLA-4 (r = 0.436), FGFR2 (r = 0.354), FGFR3 (r = 0.36), and IDO1 (r = 0.387) in HCC, suggesting that targeting STAT1 may improve the efficacy of immunotherapy for hepatocellular carcinoma." (PMID 35646925, 2022). "In a murine hepatocellular carcinoma model, an HDAC inhibitor, belinostat, activated the antitumor action against hepatocellular carcinoma in combination with anti-CTLA-4, while anti-PD-1 therapy could not obtain enough additive effect of the HDAC inhibitor against hepatocellular carcinoma." (PMID 35163049, 2022).